CD24 (CD24 molecule)
Diseases named in the same sentence as CD24 in open-access papers (continued):
Sharing a sentence is not in itself a finding about the gene and the disease.
cancer (continued). "Then, we evaluated the expression of c-Myc, CD44, CD24, CD133, and ALDH1A1 of sixty primary cancers and paired lymph nodes with cancer evasion." (PMID 37353799, 2023). "So far, several stemness markers, such as CD44, CD24, and CD133, have been used to identify cancer stem cells in pre-clinical models." (PMID 37443350, 2023). "Sphere formation assay revealed that fisetin reduced the cancer stemness promoted by gemcitabine in human PANC-1 cells and KPC mice KPC203 cells, as well as the proportion of CD44+/CD24+ cells among PANC-1 cells, further proving the results." (PMID 37743465, 2023). "In previous studies, it has been reported that YBX1 promoted the growth of cancer stem cell population and seemed to modulate the expression of numerous stemness genes, including SOX2, CD10, CD24, and CD44." (PMID 36805592, 2023). "These nanoreactors exhibited the ability to reactivate T cells and infiltrating macrophages by blocking the CD24-Siglec-10 and PD-L1-PD1 signaling pathways, leading to the secretion of IFN-γ and enhanced cancer cell killing." (PMID 37875918, 2023). "Our data suggest that the robust cancer-specific hypermethylation in the promoter regions of CD133, CD147, and CD24 by bisulfite genomic sequencing analysis is in direct agreement with our MSP results in OSCC cell lines." (PMID 36498950, 2022). "Given that EGFR and CD24 are already proposed and in the process of being therapeutically exploited, we now propose VCAM1 as a novel biomarker and target for cancer-specific stratified immunotherapy." (PMID 36221114, 2022). "CD44 has been introduced as a cancer stem cells marker in HCC together with CD90, CD133, CD24, and EpCAM, and is reported to be involved in tumor initiation and growth, cancer progression, and promoting metastasis." (PMID 35164326, 2022). "Some of the first markers identified in cancer stem cells were CD44, CD24, and later an enzyme aldehyde dehydrogenase (ALDH or ALDH1); these markers were studied with fluorescence-activated cell sorting or immune selection methodologies." (PMID 36120232, 2022). "Emerging evidence indicates that lipid raft levels are significantly enriched in CSCs compared to cancer cells and that most CSC markers such as CD24, CD44, and CD133 are located in lipid rafts." (PMID 36042526, 2022). "Immunohistochemistry (IHC) and proteomic analysis showed pronounced decrease in cancer stem cell biomarkers (CCD117, CD34, Oct-4, CD44, and CD-24) and metastatic biomarkers such as Notch-1." (PMID 35335986, 2022). "The EVs have several cancer-related markers including CD24, CD29, CD44 and CD146, proteins of potential interest as biomarkers as well as to increase the understanding of the mechanisms of cancer biology." (PMID 35012489, 2022). "For human CD24+ MDSC-DCs induction, we first collected peripheral blood samples of CRC patients in TNM Classification of Malignant Tumors (TNM) stage III or IV and enriched myeloid cells by Ficoll density gradient centrifugation." (PMID 35707772, 2022). "Gene expression analysis showed that epithelial cells in type 3 TETs expressed high levels of cancer stem cell (CSC)-related markers (NOTCH2, CD24, ALDH1B1 and PROM1)." (PMID 36115836, 2022). "However, the loss of CD24 expression does not appear to be necessary for cancer stemness." (PMID 36013184, 2022). "As demonstrated in the top DEGs, specifically cancer stem lineage clusters expressed high levels of stemness feature genes (MKI67, CD44, CD24, and PROM1) and key DEeRNAs (PHLDA1 and RASD1)." (PMID 36092920, 2022). "Upon treatment with CD24-mIgG1 antibody (clone SN3), prominent phagocytosis of cancer cells by M2c macrophages was detected with engulfment of several cancer cells per single macrophage in some donors." (PMID 35625912, 2022). "Several molecules such as CD24, CD44, and CD133 have been recognized as CSC markers for certain cancer types; however, the roles of these markers are ambiguous." (PMID 35395804, 2022).
cancer (continued). "We characterized the Panc1 cancer stem cells through the expression of canonical surface stem cell markers, namely CD44, CD24, and ESA." (PMID 35634239, 2022). "Here, we investigated the transcriptional silencing of the CD24, CD44, CD133, and CD147 genes, which are well-known cancer stem cell surface markers in various cancer types, including OSCC." (PMID 36498950, 2022). "The glycosylphosphatidylinositol (GPI)–anchored glycoprotein CD24, a typical raft protein, is highly expressed in CSCs and is considered a CSC marker that maintains cancer stemness." (PMID 36042526, 2022). "In other words, CD24 can be modified like CD47, or as a complement to CD47, blocked in cancer cells expressing CD47 and CD24 simultaneously." (PMID 36297672, 2022). "CD24 in combination with CD44 and/or CD133 (PROM1) has been highlighted as cancer stem cell markers (in combination with NANOG, OCT3/4, and SOX2), and a cell‐type‐dependent correlation of CD24 to the chemokine receptor CD184 (CXCR4) has been shown." (PMID 34293822, 2022). "To further verify ERK pathway involvement in the regulation of cancer stemness, we analysed the stem surface markers of CD133, CD44, and CD24." (PMID 36386200, 2022). "The methylation of CD133, CD147, and CD24 was observed in 70%, 75%, and 75% of the primary OSCC tumors, respectively, confirming a cancer-specific methylation pattern of these CSC surface markers." (PMID 36498950, 2022). "In addition, it is suggested that CD24/SIGLEC10 might be a target for cancer immunotherapy." (PMID 35688160, 2022). "The purpose of this article is to provide a better understanding of specific markers such as CD44+/CD24-low and ALDH enzymes in cancer stem cells in the prognosis of TNBC." (PMID 36120232, 2022). "In breast cancer, there are two types of cancer stem cells: CD44+/CD24 mesenchymal-like cancer stem cells and aldehyde dehydrogenase 1 family, member A1 (ALDH1) positive epithelial-like cancer stem cells." (PMID 35328602, 2022). "Specifically, in preclinical studies, the CD24 antibody clone SN3 was reported to block CD24/Siglec-10 inhibitory signaling and potentiate macrophage-mediated phagocytosis of carcinoma cells." (PMID 35625912, 2022). "This increase in phagocytosis was again positively correlated with the levels of CD24 expression (Pearson’s r = 0.82), with CD24 expression of some carcinoma cell lines being higher than on UPN-1, the highest CD24-expressing MCL cell line tested." (PMID 35625912, 2022). "Treatment with CD24 mAb was superior to CD47 mAb in MCL and was comparable in magnitude to the effect observed in carcinoma lines." (PMID 35625912, 2022). "The robust increase in phagocytosis upon CD24 mAb treatment was not limited to MCL and was also detected in a panel of carcinoma cell lines expressing CD24." (PMID 35625912, 2022). "The surface marker proteins used extensively to identify cancer stem cells include the transmembrane glycoprotein, CD44, the cell adhesion protein, CD24, and the cytosolic enzyme, ALDH-1, which oxidizes aldehydes to carboxylic acids." (PMID 33804152, 2021). "In total, we identified 341 up-regulated genes, including CD24 and CD44, and 138 down-regulated genes in CSCs from both primary cancers." (PMID 33995647, 2021). "We have found that compound 1 significantly decreased the number and percentage of CD15s+ cells within three subpopulations: CD44+CD24− cancer stem cells, CD44− epithelial cells, and CD44+CD24+ cells that exhibit mesenchymal and epithelial features." (PMID 34206154, 2021). "Regorafenib resistant cells (RRCs) also show increased expression of several mesenchymal genes along with an induction of CD24 and CD133 cancer stem cell markers." (PMID 34458250, 2021). "Further PCR analysis also indicated decreased mRNA levels of cancer stem cell biomarkers in 25 μM AB4 treated HCT116/FU sphere cells, including LGR5, CD133, CD24 and POU5F1." (PMID 34890366, 2021).
cancer (continued). "They both contained low proliferative AD cells with an additional strong EpCAM, CD24, CD133 staining, suggesting a cancer stem cell phenotype." (PMID 34060699, 2021). "To determine the effect of LR004-VC-MMAE on CSCs, we first investigated the fraction of CSCs by assessing the expression of CSC markers CD44, CD24 and CD133 in cancer cells by flow cytometry." (PMID 34879870, 2021). "Upon arriving in the bones, cancer cells migrate and take on stem-like or tumorigenic properties, as aided through Wnt or β-catenin signaling involving CHD11, CD24, and Wnt5A." (PMID 34685470, 2021). "Spheroids were collected to evaluate the cancer stem cells (CSCs) markers, such as EPCAM, CD133, and CD24, in HMGB1/RICTOR manipulated cells using real-time PCR methods." (PMID 34916485, 2021). "We next screened the cell lines for cancer stem cell markers by staining for CD44, CD24 and prominin-1 (CD133)." (PMID 33924486, 2021). "The data indicate significance of the CD24 vs. CD44 expression pattern on various cancer cells and attribute early progenitor/stem cell properties to the CD44+/CD24- population." (PMID 34019593, 2021). "CD24, CD44, and CD133 expression decreased after SPNs treatment both in PANC-1 spheroid cells and PANC-1 cancer cell line." (PMID 34094034, 2021). "Regorafenib resistant cells also have increased mesenchymal gene expression along with an induction of CD24 and CD133 cancer stem cell markers." (PMID 34458250, 2021). "While some cell surface markers, such as CD44, CD24, and CD133, have been identified as common CSC markers for almost all cancer types, CSC in GC and EC cancers present their specific markers as well." (PMID 34012400, 2021). "The interaction of platelets with cancer cells is also mediated by P-selectin, which binds to appropriate ligands, e.g. CD24 and CD44 on cancers." (PMID 33146401, 2021). "“Don’t eat me signals” are proteins that are upregulated on cancer cells and help them avoid the immune response, among which the best studied are CD47, PD-L1 but also CD24 and MHC-I." (PMID 33919517, 2021). "Results demonstrate that the extract, at IC50 doses, was able to significantly decrease the expression of CD44, CD24, NANOG, SOX-2, and OCT-4, indicating a reduction in the amount of cancer stem cells (CSCs) in the culture." (PMID 33572111, 2021). "Over 8–12 months, regorafenib treated HuH7 cells developed acquired regorafenib resistance and exhibited increased mesenchymal gene expression along with an induction of CD24 and CD133 cancer stem cell markers." (PMID 34458250, 2021). "We identified the cancer cells with stem-like characteristics in DU145 and PC3 cells as the CD44+/CD24- subpopulation." (PMID 33661931, 2021). "To date, the known representative markers of cancer stem cells (CSCs) comprise CD44, CD24, CD105, and CD133, and additional surface traits are typically tissue-specific." (PMID 34062950, 2021). "Few cancer cell lines have been actually classified as being CD44-positive and CD24-negative (CD44+/CD24−), thus questioning the significance of CD24 as a CSC surface marker." (PMID 33806857, 2021). "Recent breakthroughs have highlighted phagocytosis checkpoint axes which can be targeted to induce the anti-cancer functions of macrophages, such as the CD47-SIRPα phagocytosis axis, PD1-PDL1 axis, MHC I–LILRB1 axis, and CD24–Siglec-10 axis." (PMID 33790906, 2021). "qRT‐PCR showed that circFAT1 KD significantly inhibited the expression of the cancer stemness‐related genes, including SOX2, KLF4, MET, BMI1, CD24, OCT4, and ALDH1, in ALDHhigh SCC23 cells." (PMID 34258151, 2021). "CSCs and non-CSCs subpopulations were counted by flow cytometry using the cancer stem cell markers CD44 and CD24." (PMID 34242345, 2021). "The cancer cell stemness can be assessed by mammosphere forming efficiency and the cancer stem cells surface marker CD44+CD24-/low subpopulation." (PMID 34386417, 2021).
cancer (continued). "To identify a cancer stem-cell-like subpopulation in MDA-MB-231 spheroid cells, we included stem cell markers, such as CD133, CD90, CD44, and CD24, and stem cell transcription factors such as SOX9 and Nanog." (PMID 34831064, 2021). "Consistent with its potential role in cancer cell dissemination, CD44 was upregulated in CTCs in three of four models, while CD24 was downregulated in two of four models." (PMID 34206049, 2021). "The combined treatment of CD24-targeted lentivirus particles together with INS or INR2 peptides led to pancreatic (left, black bars) and lung (right, black bars) cancer cell death, as demonstrated by WST-1 (left) and MTT (right) enzymatic assays." (PMID 33958722, 2021). "In a previous work of our research group, we evaluated the role of several KIF11 inhibitors on cancer stem cell (CSC) population in MDA-MB-231 cells throughout the analysis of CD44 and CD24 expression." (PMID 34548908, 2021). "Compared with that in the normal tissues, the expression of CD24, CD90, EpCAM, CACNA2D1, and CD133 was found highly expressed in the cancer tissues." (PMID 33707423, 2021). "Moreover, OC cell lines treated with anti-CD24-CAR NK cell therapy stimulated targeted cytotoxic activity against cancer cells, suggesting that anti-CD24 therapy may hold promise as a novel immunotherapeutic approach to be validated in future OC clinical trials." (PMID 34944851, 2021). "Small divergences were observed, such as a decrease of CD166 positive cells and an increase in CD24 and CD26 in HT29hTNFa carcinoma cells." (PMID 33957885, 2021). "In this experiment, sumac significantly reduced expression levels of CD24, ALDH1, and EpCam in cancer cells." (PMID 33375383, 2020). "QGP-1 spheroid cells exhibited cancer stem cell-like features, including expression of stem cell markers such as OCT4, SOX2, and CD24." (PMID 33182509, 2020). "In our previous report, we also demonstrated that spheroids are enriched with cancer stem cells by showing the elevation of many stem cell markers, ALDH1, CD133, CD24, and SOX2 that is in line with our current study." (PMID 32046751, 2020). "Cancer cells evade phagocytosis by TAMs through the expression of the “don’t eat me”-receptors CD47, PD-L1, MHC-I β2 microglobulin subunit (b2m), and CD24." (PMID 33260974, 2020). "TNBC cancer stem cells (CSC) feature enhanced proliferative capacity, refractory treatment which leads to recurrence and metastasis (CD-24, CD-44)." (PMID 32245065, 2020). "However, a recent meta-analysis of CD24 SNPs and cancer risk was non-confirmatory." (PMID 33065994, 2020). "In brief, flow cytometry data showed that parental cancer cell lines and all investigated hybrid clones exhibited a rather identical CD44/CD24 expression pattern with more than 95% of CD44+/CD24−/low cells." (PMID 32430004, 2020). "Concerning CD24 and CD44, used to identify the cancer stem cells, MCCL-9 and MCCL-11 cells were CD24−/CD44+, whereas the MKL-1 cell line displayed a CD24+/CD44− profile." (PMID 32005907, 2020). "By using different parameters to evaluate biomarkers of cancer stemness, such as overexpression of CSC markers, elevated CD44/CD24 ratios, self-renewal capabilities and high invasion potentials, we found that JQ1 can jeopardize stemness in TNBC." (PMID 32166583, 2020). "As spheroid formation is a key attribute of cancer stem cells (CSCs), and points towards the presence of cancer stem cell-like properties, we analyzed accepted CSC markers (CD44 / CD24)." (PMID 32276641, 2020). "Various exosome types circulate in the blood of healthy donors and patients with different cancers, and surface proteins mainly represented by CD9, CD24, CD63 and CD81 are considered as universal markers of blood exosomes." (PMID 32218180, 2020). "For the purposes of cytometry assays and sorting, we defined CCD133−/CD24+/CD9−as neuronal cancer cells, CD9+/CD44+/CD133− as astro-mesenchymal cancer cells, and CD9+/CD133+ as progenitor cancer cells." (PMID 32641768, 2020).
cancer (continued). "Significance of AR expression was correlated with prognostic biomarkers including cancer stem cell markers (CD44, CD24, and ALDH1), basal markers (CK5, CK14, and nestin), proliferation marker (ki-67), apoptotic marker (Bcl-2), and COX-2." (PMID 32850312, 2020). "The findings revealed that ALDH, CD24, CD44, and CD90 were highly expressed in the isolated cancer stem cells." (PMID 32314522, 2020). "In our study, stem cell markers (CD44, CD24 and CD133) decreased after SPNs induction in MIA PaCa-2 cancer cells." (PMID 32489562, 2020). "CD24 was also reported to be related to EMT, which is an important step leading to invasion, migration, and resistance to apoptosis of various cancer cells." (PMID 33298865, 2020). "The results showed that after sphere culture, the spherical cells express higher levels of CD24, CD44, and CD133 than HT-29 cancer cells." (PMID 30770752, 2019). "Studies of neoplastic tissues have provided evidence of stem-like cells within tumors, of breast (CD44+CD24−/low), pancreatic (CD44+CD24+ESA+), brain (CD133+), head and neck (CD44+), and colon (CD133+ and CD44+ESAhigh) cancer." (PMID 30959764, 2019). "In order to study possible changes in putative cancer stem cell markers due to HNE-pretreated collagen and due to multiple HNE treatments, the expression of CD44, CD24, and ALDH was assessed." (PMID 31835715, 2019). "Previous studies also indicate that CD24 regulated EGFR signaling by inhibiting EGFR internalization and degradation in cancer cells." (PMID 31624236, 2019). "We aimed to develop a novel anti-CD24 chimeric antigen receptor (CAR) as an immunotherapeutic approach against OC cells and cancer stem cells (CSC)." (PMID 30717444, 2019). "Induced overexpression of miR-136 inhibited sphere formation, enhanced the sensitivity of OC cells to chemotherapy, and decreased the expression level of cancer stem cell markers including CD133, CD24, and ALDH1." (PMID 31530793, 2019). "Cell viability, proliferation, apoptosis and the expression of different cancer stem cell markers (CD133, CD24, CD44, CD29, CD73 and CD105) were analysed." (PMID 31371743, 2019). "To identify the cancer stem cell (CSC) subpopulation, we analyzed expression ofthe markers CD44 and CD24 by flow cytometry." (PMID 31384244, 2019). "PDAC cancer cells are composed of different subpopulations, such as epithelial cancer cells, CD24+/CD44+ cancer stem cells, CD133+ cancer stem cells, and mesenchymal cancer cells; furthermore, each cell population is genetically heterogeneous." (PMID 31275385, 2019). "CSCs, depended on cancer types, occupied different markers, such as, SOX2, CD133, epithelial cell adhesion molecule (EpCAM), CD166, CD24, CD29, Lgr5, Kruppel-like factor 4 (Klf4) and ALDH." (PMID 30962766, 2019). "We quantified by an ELISA-based technique specific proteins of cancer-derived exosomes (CD44,CD44v6,EpCAM,CD9,CD81,Tspan8,Integrin α6,Integrin β4,CD24,CXCR4)." (PMID 31048929, 2019). "HT29 cell line was identified as cancer stem-like cells with the high expression of CSCs markers CD44 and CD24." (PMID 31640758, 2019). "However, CD24 has been implicated in numerous cancer types so it may serve as a general cancer marker and not as a specific biomarker for BC." (PMID 31281356, 2019). "Consistent with this, in the CEA-positive subgroup, of which the carcinomas expressed DAXX at low levels, they were significantly correlated with CD24 expression (rho = 0.461, p < 0.005)." (PMID 31614769, 2019). "EVs carry molecules such as CD24, and epithelial cell adhesion molecule (EPCAM1), which directly regulate cancer-cell migration, proteases (MMP2, MMP9), which promote ECM degradation and cancer invasiveness, or EV-associated mRNAs, such as miR21, which may induce resistance to paclitaxel." (PMID 30200478, 2018).